B2M (beta-2-microglobulin)
Diseases named in the same sentence as B2M in open-access papers (continued):
Sharing a sentence is not in itself a finding about the gene and the disease.
tumor (continued). "In the absence of B2M, such MHC-I complex formation and cell surface presentation will be abolished/compromised, thereby minimizing any cellular immunity actions to any foreign/tumor entities." (PMID 40563082, 2025). "By downregulating MHC class I expression or interfering with antigen processing pathways, such as by lacking TAP or losing beta-2 microglobulin (B2M), which impairs peptide presentation and decreases visibility to CD8+ T cells, tumor cells avoid immune detection." (PMID 40514725, 2025). "On the basis of B2m-KD, FAM114A1-KD did not further enhance the immune killing of tumor cells." (PMID 41249116, 2025). "However, the absence of B2m, Jak1 or LMP2 expression on EMT6 tumor cells did not impact the frequency of macrophages, effector CD4+ or CD8+ T cells, or Tregs in the TME." (PMID 38427670, 2024). "Similarly, the expression of TAP2, TAPBP, PSMB8, and B2M was each shown to be induced by VC treatment in the WT, but not TET2-KO, tumor cells." (PMID 39388288, 2024). "Tumors lacking B2M grew moderately faster than wt tumors (mean tumor weight at d14 PK5L1940 42.8 mg PK5L1940 B2M−/− 90.8 p < 0.01) suggesting that although wt tumors have low basal MHCI, CD8 T cell immunosurveillance regulates tumor growth in this model." (PMID 37072485, 2023). "Although not a component of the IFN-γ pathway, B2M was included because of its role in MHC-I presentation and anti-tumor immunity, but it was not a hit in our initial IFN-γ survival screens as B2M variants should not have an effect on cell proliferation in vitro." (PMID 36669486, 2023). "H-2Db, H-2Kb, and B2M expression were significantly increased compared to non-treated controls, indicating that the MHC class I antigen processing and presentation machinery was functional in these tumor organoids." (PMID 37746286, 2023). "However, alterations in the APM, such as downregulation of MHC-I molecule expression or the absence of beta-2-microglobulin (B2M), limit the presentation of antigen peptide-MHC class I complexes in the presence of tumor antigens." (PMID 33859752, 2021). "Fortunately, the non-cycling dormant human tumor cells in BC159-T#3, also observed in tipifarnib-treated PDX, showed upregulation of antigen presenting molecules, such as class I MHC and B2M, which play a critical role in the presentation of tumor antigens for the recognition of tumor cells by CTLs." (PMID 32460812, 2020). "In addition, RARRES3 expression in primary tumors did not lead to differences in the number of circulating tumor cells, as measured by relative levels of human GAPDH to murine B2M." (PMID 24867881, 2014). "To assess whether tumor killing occurs within CRATERs, we performed a whole-mount terminal deoxynucleotidyl transferase dUTP nick end labeling (TUNEL) assay, enabling a 3D view of the tumor surface, on CpG ODN-treated vs. PBS- or non-treated tumors and B2M-intact or B2M-depleted tumors." (PMID 41109214, 2025). "Although B2M, MAPK1, and SMAD4, which are also driver genes, could not be pooled in the meta-analysis, they correlated with neoplasm histologic grade, pathologic stage and N status, final vital status, and HPV status in OSCC as demonstrated by TCGA clinical and pathological correlation analysis." (PMID 36923449, 2023). "To determine whether this expression indeed reflect transcript levels in MCC cells and not cells of the tumor microenvironment, we analyzed the four MCC cell lines with varying degrees of HLA-A surface expression for gene expression of HLA-A, B2M, and the APM components." (PMID 28536458, 2017).
cancer (231 papers, 1990 to 2026). A tumor composed of atypical neoplastic, often pleomorphic cells that invade other tissues. "Loss of B2M has been discovered to be a major factor for cancer immune evasion via downregulating MHC class I expression." (PMID 40047437, 2025). "Biallelic loss, loss of heterozygosity, point mutations and epigenetic silencing of the B2M gene that result in MHCI deficiency are frequently encountered across several human cancers and are thought to be contributory to ICI resistance." (PMID 40560386, 2025). "Secondly, while CD4+ T cells, NK cells, and γδ T cells have been identified as key effector cells for ICB treatment in B2M-deficient cancers, the underlying mechanisms by which these cells mediate their cytotoxic effects remain to be fully elucidated." (PMID 40191187, 2025). "Blunted antigen presentation due to MHCI deficiencies resulting from B2M loss of function is thought to be a major cause of ICI resistance in many human cancer types." (PMID 40321762, 2025). "Collectively, radiotherapy holds the potential to serve as a promising alternative for reversing immune resistance in B2M/MHC-I-deficient cancer patients." (PMID 40191187, 2025). "We noted a paucity of HLA class I expression on the cancer cell line and identified a single-nucleotide variant resulting in a missense mutation in the B2M gene (c.92C>G) on whole-exome sequencing analysis." (PMID 41415427, 2025). "For example, beta-2-microglobulin (B2M) mutations were all clonal (n = 4), and matched RNA-seq revealed significantly decreased B2M expression in these cancers, confirming the impact of these mutations." (PMID 41193656, 2025). "Gene therapy for B2M deficiency is an important therapeutic and medication option for the treatment of malignant tumors." (PMID 37165489, 2024). "We found that the medium expression of B2M and most of the HLA alleles decreased in both cancer subtypes compared to adjacent normal tissues." (PMID 38281021, 2024). "Alteration of B2M is common across different cancer types, and evidence suggests that B2M loss drives poor response to immunotherapy through disruption of MHC class I protein expression at the cell surface." (PMID 38751776, 2024). "A striking example was observed in the research in which MSI cancer patients tend to have a higher mutation frequency in the B2M gene." (PMID 38041084, 2023). "ICB substantially increased the frequency of γδ T cells in B2M-deficient MMRd cancers, expressing high levels of PD-1, cytotoxic molecules, and killer-cell immunoglobulin-like receptors." (PMID 37492581, 2023). "In B2M-deficient cancers, γδ T cells showed frequent intraepithelial localization and expression of CD103 (tissue-residency), CD39 (activation), granzyme B (cytotoxicity) and Ki-67 (proliferation), as well as PD-1, consistent with the scRNA-seq data." (PMID 36631610, 2023). "MHC-I has been demonstrated to be an inhibitory receptor of NK cells, and loss of MHC-I on the cell surface due to B2M loss would render cancer cells more vulnerable to NK cells." (PMID 37098551, 2023). "MHC-I has been demonstrated to be an inhibitory receptor for NK cells, and loss of cell surface MHC-I due to B2M loss by cancer cells would render cancer cells more vulnerable to NK cells." (PMID 33658560, 2021). "The B2M gene is commonly mutated across multiple cancers with the highest mutation rate reported in uterine, stomach, colorectal and breast cancer." (PMID 34201655, 2021). "Our study demonstrates that in stage IV GI MSI cancers peritoneal metastasis is closely associated with B2M mutations." (PMID 34168989, 2021). "Gene mutation in antigen-presenting protein beta-2-microglobulin (B2M) leads to the loss of MHC I presentation in cancer cells, contributing to escape from CD8+ T cell immune surveillance." (PMID 33514004, 2021). "Considering that metastatic MSI cancers represent two distinct subgroups depending on B2M mutation status, the impact of B2M mutation status on response to ICB needs to be reconsidered." (PMID 34168989, 2021).
cancer (continued). "That and the recent finding of frequent somatic mutation of the MHC class I receptor component B2M in canine cancer have strong biomarker and therapeutic implications." (PMID 30890123, 2019). "We then performed a cancer-specific analysis of 3514 patients across 8 solid tumor types with at least 5 somatic B2M and HLA mutations." (PMID 31345234, 2019). "B2M mutations are more frequent for melanoma, bladder, gastric, and lung cancer in particular, with 27–50% found for these cancers in The Cancer Genome Atlas dataset compared with 1.8% across all tumor types." (PMID 30002656, 2018). "We discovered two B2M frameshift mutations, p.Ser14fs (50–90% of cancer cells) and p.Gly63fs (70–90% of cancer cells), in progression samples of PatT33, who initially responded for 1 year to ipilimumab." (PMID 29070816, 2017). "Due to this deletion/LOH and upstream frameshift mutations in B2M, the majority of cancer cells in progression samples were likely to be B2M deficient." (PMID 29070816, 2017). "It has been shown that B2M is a biomarker of inflammation, while the inflammation is associated with cancers." (PMID 26983758, 2016). "The current study showed the overexpression of B2M in human epithelial-type borderline and malignant tumours and evaluated the expression of B2M associated with clinicopathological features in patients with EOC." (PMID 26983758, 2016). "However, emerging evidence suggests that B2M expression is frequently compromised in numerous cancers due to deficiency, mutation and epigenetic suppression, and B2M alterations are associated with low response rates." (PMID 40191187, 2025). "Specifically, further research is needed to ascertain whether the alterations in HLA-E, B2M, and HLA-B, as indicated in our findings, are indeed linked to cancer immune evasion through the loss of MHC Class I antigen presentation." (PMID 38256174, 2024). "The authors were able to confirm that B2M mutated MMR-d cancers derived clinical benefit from treatment with anti-PD-1 therapy, which demonstrates that in tumors that lack MHC class I antigen presentation, other immune effectors such as γδ T cells can mediate response to PD-1 blockade." (PMID 38321065, 2024). "Moreover, total HLA Class I antigen loss due to the mutation of beta-2 microglobulin (B2M) – a component of HLA Class I molecules, has been found in several types of cancer." (PMID 38281021, 2024). "Thus, B2M alterations are associated with a high clinical benefit rate of PD-1 blockade in patients with MMR-d cancers." (PMID 36631610, 2023). "In addition, a newly generated truncating B2M mutation was reported in two patients with brain metastasis among five patients with advanced mismatch repair-deficient cancers who demonstrated acquired resistance to anti-PD-1 therapy." (PMID 37614504, 2023). "The MSI group shows mutations in major histocompatibility genes, including beta-2 microglobulin (B2M), which may reduce antigen presentation in these highly mutated cancers." (PMID 35323320, 2022). "MSI cancers commonly present with B2M mutations as a mechanism of immune evasion." (PMID 34168989, 2021). "B2M mutations and loss of B2M expression were detected in 6 out of 25 stage IV MSI cancers." (PMID 34168989, 2021). "Moreover, while the impairment of antigen presentation in immune hot tumors is shared across cancer types, the association of B2M loss with response and the overall low PD1 and PDL1 expression are specific traits of CRC." (PMID 34197832, 2021). "We therefore asked whether the response to immunotherapy and the metastatic pattern of stage IV MSI cancers at the time point of diagnosis may differ depending on B2M mutation status." (PMID 34168989, 2021). "Tumor antigen presentation is essential for the immune defense of cancer, and mutations affecting pathways important for antigen presentation, e.g., beta-2-microglobuline (B2M) loss, might result in ICI resistance." (PMID 30002656, 2018).
cancer (continued). "The highest expression of B2M was found in patients with borderline and malignant tumours compared with women with normal ovary, suggesting that the overexpression of B2M may be associated with aggressive disease." (PMID 26983758, 2016). "Intrinsic cancer cell resistance represents loss of immunogenicity of cancer cells, which were suggested to result from alterations, such as loss of beta-2-microglobullin (B2M) function and phosphatase and tensin homolog deleted on chromosome 10 (PTEN) function." (PMID 33794809, 2021). "Targeting NLRC5 promoter demethylation through TRED-I system can upregulate MHC-I, B2M, TAP1 and genes encoding immune proteasome components (LMP2/PSMB9/β1i, LMP7/PSMB8/β5i), thereby enhancing CD8+T cell-mediated anti-cancer immunity." (PMID 40191187, 2025). "We also investigated the detected beta-2 microglobulin (B2M), a component of major histocompatibility complex class I molecules and frequently found elevated in blood of cancer patients." (PMID 40789452, 2025). "B2M is a commonly used reference gene for gene expression studies and particularly in cancer research." (PMID 41008620, 2025). "With regard to proteins released after sonication, several molecules were identified as candidate biomarkers in cancer US supernatants (Beta-2 microglobulin, CA125, CA19-9, CEA, CRP, Galectin-3, TIMP-1, uPA, and VEGF-A)." (PMID 40563629, 2025). "To examine the cytotoxic capacity of expanded MPE T cells, we co-cultured sorted CD8+ T cells from expanded MPE cells with CFSE-labeled, autologous cancer cells transduced with GFP or B2M." (PMID 41415427, 2025). "Previous research suggests that B2M is a promising potential target for cancer therapies in the future." (PMID 39453509, 2024). "Findings made on human cancers also revealed that cancer cells of different organs consistently express B2m-free HCs." (PMID 39057057, 2024). "To elucidate the role of HLA‐I molecules in increased NK resistance in cancer cells, we knocked out β2 microglobulin (B2M) in MB231 and MCF7 cells using the CRISPR‐Cas9 technology." (PMID 38638003, 2024). "All the studies above confirm the expression of B2m-free HCs in human cancer tissues, which are probably upregulated by proinflammatory cytokines." (PMID 39057057, 2024). "An in vivo experiment demonstrated that immunocompetent mice when treated with anti-PD-1 therapy and injected with B2M-knockout or B2M-wild type cancer cells as a control group." (PMID 38629578, 2024). "After a 48-h co-culture period, flow cytometry (FCM) was used to determine the expression of HLA-ABC and B2M in human cancer cells." (PMID 38715057, 2024). "B2M emerges as a promising therapeutic target for cancer in various solid tumors, including human lung, breast, renal, and prostate cancers." (PMID 38589404, 2024). "Beta-2-microglobulin (B2M) is a subunit of MHC I molecule and its mutations have been revealed in various cancers." (PMID 39534873, 2024). "Further observations indicated a marked decrease in the destructive capability of CD8+ T-cells against these B2M-depleted cancer cells." (PMID 38629578, 2024). "The findings of this study indicated that activated human CAFs decreased HLA-ABC and B2M expression in human cancer cells, which was reversed by Az-mediated suppression of CAF activation." (PMID 38715057, 2024). "As a subunit of MHC-I, the immunomodulatory function of B2M has been fully studied, and it is expected to become a potential target for cancer immunotherapy." (PMID 38743119, 2024). "Elevated levels of B2M in the bloodstream can indicate certain conditions like chronic inflammation, some types of cancer, or kidney dysfunction." (PMID 38474110, 2024). "Although some receptors were differentially expressed between ES-3 B2M KO-NKs and ES-3-NKs, the cytotoxicity against all cancer cell lines (K562, A2780 cis, and SKOV3) was similar." (PMID 39125777, 2024).
cancer (continued). "Using a dataset of 594 CRC patients/samples from the TCGA Pan Cancer Atlas, we looked at the percentage of alterations present in HDAC2, CIITA, and B2M based on mutations, mRNA expression levels, structural variants, and amplifications." (PMID 37046620, 2023). "We next identified a strong association between B2M inactivation and increased infiltration by γδ T cells in MMR-d cancers." (PMID 36631610, 2023). "IFN signaling exert an antiproliferative effect on the cancer cells but also contributes to MHC-I induction while B2M expression is required for MHC-I expression and antigen presentation." (PMID 37180110, 2023). "Of note, several evidences showed that modifications of B2M expression dampens antigen presentation and contribute to poor reaction to cancer immunotherapies." (PMID 36949664, 2023). "We thus knocked out B2m, a molecule crucial for MHC-I assembly, in the Pikfyve-wild-type or Pikfyve-loss cancer cells." (PMID 38011559, 2023). "Cancer vaccination with ODN1862 adjuvant was only marginally effective in MHC-I-negative models that deleted the B2M gene in TC-1 cell line." (PMID 38041084, 2023). "In MMRd cancers, expression of MHC-I alleles, as well as other components of antigen presentation machinery, such as beta 2 microglobulin (B2M) and TAP2, are commonly disrupted." (PMID 37492581, 2023). "Genetic alterations in B2M have been reported in several types of cancer that have developed acquired resistance to ICB." (PMID 37614504, 2023). "We found that cancer cells with higher levels of CNV displayed lower levels of MHC-I genes (HLA-A, HLA-B and HLA-E) and the B2M gene, suggesting that these cancer cells were less immunogenic." (PMID 36596773, 2023). "However, T-cell-based cancer vaccines may develop resistance due to the deficiency of B2M." (PMID 36046045, 2022). "An oncoprint plot showed genomic alterations in genes encoding the HLA-I, B2M, TAP1 and TAP2 that would influence antigen presentation, amounting to ~12% of 10,967 cancer patients in the TCGA data set." (PMID 36612246, 2022). "In this process, the loss of beta-2 microglobulin, which is involved in the MHCI antigen presentation pathway in cancer cells, allows cancer cells to evade recognition by T cells." (PMID 36298556, 2022). "The NPS was significantly and positively associated with HLA genes, including TAP1, HLA-E, HLA-DRA, B2M, TAP2, HLA-DPA1, and HLA-DOA in all cancers." (PMID 36170029, 2022). "B2M was involved in cytokine‐cytokine receptor interactions, proteoglycans in cancer, the NF‐kappa‐B signaling pathway, and the Toll‐like receptor signaling pathway." (PMID 33960680, 2021). "Collectively, these studies indicate that the potential of B2M as an independent prognostic indicator for cancers is tissue‐dependent." (PMID 33960680, 2021). "Recent studies have shown that in addition to the role of B2M in immunity, B2M also widely correlated with proliferation, apoptosis and metastasis of cancer cells." (PMID 33658560, 2021). "Ballhausen and colleagues collected tissue from CRC and endometrial MSI cancers and studied the immunogenicity of neo-antigens derived from coding microsatellites in B2M-wild-type tumors and B2M-mutant tumors." (PMID 34205397, 2021). "CD47 is a cell surface receptor that regulates macrophages from attacking healthy cells and is known to be overexpressed in cancers; B2M is a marker on MHC class 1 molecules; and EPCAM is a transmembrane receptor on epithelial cells that aids cell adhesion." (PMID 33690223, 2021). "Platelet markers that alter significantly in the presence of cancer have been identified as beta-2-microglobulin (B2M), pro-platelet basic protein (PPBP), thymosin beta 4 X-Linked (TMSB4X), and platelet factor 4 (PF4)." (PMID 35096878, 2021).